LINC02604 (long independently transcribed non-coding RNA 2604)
Synonyms: lncHERG
Gene: Long non-coding RNA gene on chromosome 7 (66,902,857 to 66,906,297, forward strand). Ensembl gene ENSG00000273142.
Diseases named in the same sentence as LINC02604 in open-access papers:
LINC02604 is named in the same sentence as 8 diseases in open-access papers, as found by Europe PMC text mining. Sharing a sentence is not in itself a finding about the gene and the disease.
LINC02604 shares sentences with these, for which no sentence is quoted: asthma (1 paper); breast carcinoma (1); colon cancer (1); colorectal cancer (1); glioblastoma (1); lung carcinoma (1); ovarian carcinoma (1); tumor (1).